MAGI1 (membrane associated guanylate kinase, WW and PDZ domain containing 1)
Diseases named in the same sentence as MAGI1 in open-access papers (continued):
Sharing a sentence is not in itself a finding about the gene and the disease.
viral infection (2 papers, 2012 to 2022). "In the current report, we found that IAV infection increases MAGI1 expression and enhances virus infection by inhibiting various anti-viral responses including STATs and IRF3 activation and induction of MX1 and OAS2." (PMID 36082118, 2022). "More importantly, the pre-treatment of OxLDL upregulates virus infection in ECs, suggesting that the induction of MAGI1 by OxLDL increases EC activation and accelerates virus infection by inhibiting IAV-mediated anti-viral responses." (PMID 36082118, 2022). "Since we find that virus infection upregulated MAGI1 expression, this increased MAGI1 expression provides a favorable environment for virus to replicate and thereby forming a positive feedback loop." (PMID 36082118, 2022). "Our results suggest that IAV and/or OxLDL-induced MAGI1 expression accelerates virus infection in ECs and that MAGI1 depletion effectively inhibits this process." (PMID 36082118, 2022). "The high z-score predicts that MAGI1 depletion will down-regulate the expression of genes belonging to the viral infection category." (PMID 36082118, 2022). "Taken together, these data suggest a possible role for MAGI1 in IAV-associated cardiovascular and acute respiratory disease in dyslipidemia patients through driving virus infection." (PMID 36082118, 2022). "Thus, MAGI1 as a promotor of both EC activation and virus infection, is a potential therapeutic target for influenza virus infection." (PMID 36082118, 2022). "Our study shows that MAGI1 also promotes virus infection, presumably via its interaction with PBM." (PMID 36082118, 2022). "Thus, MAGI1 depletion should break this cycle and suppress virus infection and replication." (PMID 36082118, 2022). "Since MAGI1 depletion robustly inhibits IAV infection, MAGI1's role in supporting virus infection is larger than that of Scribble and Dlg1." (PMID 36082118, 2022). "MAGI1 has six PDZ domains, thus, it is possible that the binding between the virus NS1 PBM and MAGI1 plays a major role in viral infection and replication." (PMID 36082118, 2022). "MAGI-1 clearly regulates processes important for viral infection, as in addition to being targeted by the NS1 ESEV PBM, MAGI-1 is targeted by the PBMs of the adenovirus E4-ORF1 and HPV E6 proteins." (PMID 22911767, 2012).
adult T-cell leukemia (1 paper, 2021). "Additionally, MAGI1 has been described to bind to the adenoviral E4-ORF1, the high-risk HPV E6 oncoproteins, and to Tax1, an oncoprotein encoded by the human T-cell leukemia virus type 1 (HTLV-1), the etiological agent of adult T-cell leukemia (ATL)." (PMID 34198584, 2021).
COVID-19 (1 paper, 2022). A disease caused by infection with severe acute respiratory syndrome coronavirus 2. "After comparing the significant genes in T2D and COVID-19, five genes were found to be shared between T2D and COVID-19: PTPRD, CSMD1, MAGI1, ASIC2, DAB1." (PMID 36482905, 2022). "Further, in our gene-based analysis, five genes (DAB1, ASIC2, MAGI1, CSMD1 and PTPRD) were shared between T2D and COVID-19." (PMID 36482905, 2022).
dyslipidemia (1 paper, 2022). "The data collectively provides insights into the role of MAGI1 in influenza infection as well as associated cardiovascular disease observed in dyslipidemia patients." (PMID 36082118, 2022).
glioblastoma (1 paper, 2021). The most malignant astrocytic tumor (WHO grade IV). "Similarly, restitution of MAGI1 expression in glioblastoma cell lines decreases proliferation, migration, and invasion through AKT, MMP2, MMP9, and the E-cadherin/ N-cadherin/vimentin pathway." (PMID 34503076, 2021). "Similarly, downregulation of MAGI1 in the PTEN defective U87MG and U251 glioblastoma cell lines enhances the accumulation of β-catenin, increases the expression of mesenchymal biomarkers, stimulates cell proliferation, and reduces cell apoptosis." (PMID 34503076, 2021).
Hypercholesterolemia (1 paper, 2022). An increased concentration of cholesterol in the blood. "Influenza replication is increased by OxLDL pre-treatment, Whereas, MAGI1 depletion decreased virus replication, suggesting the crucial role of IAV-induced MAGI1 expression in promoting IAV infection in hypercholesterolemia patients." (PMID 36082118, 2022).
in in situ carcinomas (1 paper, 2024). "In contrast, in histological samples, a change in subcellular localization from the cytoplasm in low-grade squamous intraepithelial lesions (LSIL) to the nucleus in the high-grade squamous intraepithelial lesion (HSIL) was observed; in in situ carcinomas and ISCC, MAGI-1 expression was absent." (PMID 38927930, 2024).
infantile spasms (1 paper, 2020). A rare epilepsy syndrome characterized by onset of epileptic spasms in infants between 2 and 12 months of age, and rarely up to 24 months. "In addition, the two patients with SYN2 and MAGI1 variations in our datasets experienced infantile spasms." (PMID 33584793, 2020).
Insulin resistance (1 paper, 2025). Increased resistance towards insulin, that is, diminished effectiveness of insulin in reducing blood glucose levels. "The MAGI1 gene has also been suggested to be associated with insulin resistance and glucose response in humans." (PMID 39754479, 2025).
invasive breast carcinoma (1 paper, 2020). A carcinoma that infiltrates the breast parenchyma. "Only CTHRC1 and LPAR5 were upregulated and MAGI1 was downregulated in lung adenocarcinoma, thyroid carcinoma, and kidney and renal papillary cell carcinoma in addition to invasive breast cancer when these genes were queried from TCGA database." (PMID 32539762, 2020).
liver cancer (1 paper, 2023). An epithelial or non-epithelial malignant neoplasm that arises from the liver. "In liver cancer, TMEM220-AS1 functions as a competitive endogenous RNA by regulating the miR-484/MAGI1 axis to inhibit tumor progression." (PMID 37686677, 2023).
localized scleroderma (1 paper, 2026). Localized scleroderma is the skin localized form of scleroderma characterized by fibrosis of the skin causing cutaneous plaques or strips. "In the present study, we investigated the role of transgenic human MAGI1 in endothelial cells in animal models of localized scleroderma and systemic sclerosis." (PMID 41814414, 2026).
lymphocytic leukemia (1 paper, 2021). "Methylation of multiple CpG islands of MAGI1 promoter is associated with a worse overall survival of patients with lymphocytic leukemia." (PMID 34503076, 2021). "In renal, liver, and gastric cancers and in lymphocytic leukemia, MAGI1 downregulation is associated with a poor prognosis." (PMID 34503076, 2021).
ovarian carcinoma (1 paper, 2023). A malignant neoplasm originating from the surface ovarian epithelium. "Because MCF7 MAGI1 KO cells showed defects in their DNA repair machinery, we tested whether olaparib, a PARP1 inhibitor used in patients to treat certain subtypes of breast and ovarian cancers, would render MCF7 MAGI1 KO cells more sensitive to cisplatin." (PMID 37566008, 2023).
psoriatic arthritis (1 paper, 2023). Joint inflammation associated with psoriasis. "On the other hand, polymorphisms in IL23R, TNFAIP3, PTPN22 (tyrosine-protein phosphatase non-receptor type 22), IL12B, RUNX1 (CD8-lymphocyte activation and differentiation), IL13, KIR (killer-cell immunoglobulin-like receptor), and MAGI1 genes have shown association with psoriatic arthritis." (PMID 37628670, 2023).
scleroderma (1 paper, 2026). Scleroderma is a rare autoimmune connective tissue disorder characterized by abnormal hardening of the skin and, sometimes, other organs. "METHODS: Wild-type and human MAGI1-overexpressing endothelial cells in mice were challenged with sodium hypochlorite or bleomycin injections to induce sclerosis/scleroderma, mimicking the human disease." (PMID 41814414, 2026). "CONCLUSIONS: The results indicate that endothelial cells expressing transgenic human MAGI1 attenuate tissue permeability and fibrotic responses in models of bleomycin- and sodium hypochlorite-induced scleroderma/sclerosis." (PMID 41814414, 2026).
tumor (30 papers, 2011 to 2025). "Membrane-associated guanylate kinase inverted 1 (MAGI1) acts as a tumor suppressor, and silencing MAGI1 notably facilitated the invasion of GC cells by promoting the expression of EMT-related molecules and MMPs by impairing MAPK/ERK signaling." (PMID 38201481, 2023). "An analysis of human BC patients’ transcriptomic data revealed that patients with low MAGI1 levels had a higher tumor mutational burden and homologous recombination deficiency." (PMID 37566008, 2023). "Loss of tight junction integrity in an HPV-positive, tumor-derived cell line results from E6-mediated degradation of MAGI-1." (PMID 27537218, 2016). "In conclusion, MAGI-1 expression could be a potential biomarker for distinguishing those cells with normal morphology but with HPV 16 integrated from those showing morphology-related uterine cervical lesions associated with tumor progression." (PMID 38927930, 2024). "hDlg, hScrib and MAGI-1 are tumour suppressors; the loss of these proteins facilitates cancer formation, and all high-risk E6 proteins target them for proteasome-mediated degradation, most likely leading to the loss of cell polarity and facilitating tumour formation." (PMID 34696321, 2021). "In conclusion, the tumor suppressor MAGI1 is emerging as an important molecule in modulating different activities in cancer cells." (PMID 37566008, 2023). "To characterize the tumor suppressive pathways and cellular events regulated by MAGI1, we deleted the MAGI1 gene in MCF7 cells and performed transcriptomics, cellular, and functional studies." (PMID 37566008, 2023). "MAGI1 (membrane-associated guanylate kinase, WW, and PDZ domain-containing protein 1), a cytoplasmic scaffolding protein with tumor suppressor functions, is lost or has its expression decreased in several cancers, including BC." (PMID 37566008, 2023). "MAGI1 appears to act as a tumour suppressor, modulating the activity of oncogenic pathways such as the PI3K/AKT and Wnt/β‐catenin pathways." (PMID 36308410, 2022). "Anecdotally, MAGI1 was identified in a screen for NSAIDs-induced molecules to target as an alternative to the long-term use of NSAIDs as tumor preventive agents." (PMID 34198584, 2021). "Experimentally, MAGI1 downregulation in ER+ BC cell lines promoted cell proliferation and survival in vitro and enhanced primary tumor growth and lung metastasis formation in vivo." (PMID 34198584, 2021). "A similar study that also evaluated the expression of MAGI1 in BC cell lines confirmed its tumor suppressive function and found a distinct molecular mechanism behind this effect." (PMID 34198584, 2021). "While significant insights have been made in confirming the critical role of MAGI1 as tumor suppressor in different cancer types, research involving MAGI1 functions in endothelial cells (ECs) remains limited." (PMID 34198584, 2021). "Immunohistochemistry also showed that TMEM220-AS1 promoted MAGI1 expression, but decreased Ki-67 expression in xenograft tumor tissues." (PMID 34422806, 2021). "Here, we review MAGI1′s role as scaffolding protein, recent developments in the understanding of MAGI1 function as tumor suppressor gene, its role in endothelial cells and its implication in cancer and vascular biology." (PMID 34198584, 2021). "Although progress has been made in understanding the role of MAGI1 as tumor suppressor or regulator of vascular functions, there are still many open questions, particularly regarding its regulation in different tissues, and its clinical relevance." (PMID 34198584, 2021). "The most intriguing emerging roles of MAGI1 are probably related to its function in vascular biology and its role in cancer as tumor suppressor." (PMID 34198584, 2021).
tumor (continued). "We verified that TMEM220-AS1 is a novel tumor suppressor that regulates HCC through the miR-484/MAGI1 axis." (PMID 34422806, 2021). "The stability of these complexes is under the control of molecular scaffolds and several signaling pathways, including the PTEN tumor suppressor, that interacts indirectly with β-catenin by binding to MAGI1-b." (PMID 34198584, 2021). "MAGI1 is downregulated in various cancers and acts as a tumor suppressor; in several cases by modulating direct or indirectly PTEN activity." (PMID 34198584, 2021). "The tumor volumes and weights in MAGI1 overexpression group were clearly inhibited compared to those in the vector group." (PMID 34422806, 2021). "One of the outstanding questions relative to MAGI1 function is how it exerts its function as tumor suppressor in different cancers." (PMID 34198584, 2021). "Here, we summarize some of the most important findings about MAGI1, in particular concerning its emerging role as vascular regulator and tumor suppressor, along with the mechanisms that regulate its expression." (PMID 34198584, 2021). "Reports have demonstrated that MAGI1 acts as a tumor suppressor by inhibiting the mitogen-activated protein kinase/extracellular signal-regulated kinase signaling pathway in GC39." (PMID 33328548, 2020). "MAGI1 downregulation in the ER+ murine BC cell line 67NR accelerates primary tumor growth and enhances experimental lung metastasis formation." (PMID 31963297, 2020). "Consistently, in the 67NR ER+ murine BC model, MAGI1 downregulation increases lung metastasis formation possibly promoting tumor cell extravasation, initial seeding and/or early survival in the lung preceding metastatic niche formation." (PMID 31963297, 2020). "Membrane-associated guanylate kinase (MAGUK) with inverted domain structure-1 (MAGI1) is an intracellular adaptor protein that stabilizes epithelial junctions consistent with a tumor suppressive function in several cancers of epithelial origin." (PMID 31963297, 2020). "The present observations reinforce the status of MAGI1 as a potential tumor suppressor downregulated during inflammation and cancer progression and upregulated by COXIBs." (PMID 31963297, 2020). "In conclusion, we have identified previously unrecognized features and functions of MAGI1 in ER+/HER2− BC: MAGI1 is highly expressed and has tumor suppressor activity in ER+/HER2− BC subset." (PMID 31963297, 2020). "Here, using a combined experimental and clinical approach, we report the identification of MAGI1 as tumor suppressor in ER+/HER2− BC with possible prognostic value for the identification of patients at high-risk of relapse within this subset." (PMID 31963297, 2020). "Because of this activity, MAGI1 is considered an important regulator for cell junctions with tumor suppressor behaviour." (PMID 26652480, 2015). "These include the four C-terminal amino acids which form a PBM motif for interaction with the hDLG and hScrib and MAGI-1 tumor suppressors, and a region involved in micronuclei formation." (PMID 23880157, 2013). "The interaction between MAGI-1 and β-catenin suppresses Wnt signaling and thereby demonstrates a tumor suppressor function." (PMID 22911767, 2012). "Importantly, celecoxib treatment in vivo increased MAGI1 levels and significantly reduced tumor growth, consistent with the findings in other tumor models." (PMID 34198584, 2021). "Conversely, overexpression of MAGI1 significantly inhibited tumor growth in vivo." (PMID 34198584, 2021). "We further observed that low MAGI1 expression is associated with higher histological grade, increased cell proliferation and reduced epithelial differentiation suggesting that MAGI1 expression is downregulated during tumor progression, consistent with previous reports." (PMID 31963297, 2020). "To experimentally assess whether MAGI1 downregulation increased tumor progression, we set up to perform in vivo tumor growth and metastasis assays." (PMID 31963297, 2020).
tumor (continued). "We therefore proposed that MAGI1 is a tumor suppressor in CRC." (PMID 31963297, 2020). "Whether MAGI1 is part of this mechanism, and whether this protein is possibly regulated by other tumor-promoting mediators of inflammation (e.g., TNF, IL6) is an attractive hypothesis that deserves further investigations." (PMID 31963297, 2020). "Moreover, PRKX binds to enzymes such as Pin-1, Magi-1 and Bag-3, which regulate cell differentiation, proliferation, apoptosis and tumor genesis." (PMID 31964936, 2020). "Considering that all of these miRNAs were up-regulated in tumor tissues in our system, we could speculate that one or more of them could block the expression of MAGI1 in HCC tissues." (PMID 26652480, 2015). "Thus it appeared that the apical junction-localized MAGI1 scaffold protein participates in multiple complexes to fine-tune adhesion and signaling, and may therefore be considered as a tumor suppressor." (PMID 33707576, 2021). "Due to the critical role of MAGI1 in regulating cell–cell contacts, it is not surprising that its loss influences the adhesion, proliferation, invasiveness, and metastasis of different tumor cell types." (PMID 34198584, 2021). "Finally, discovered interactors for MAGI1 and SCRIB were analysed with regard to new biological functions that can be linked to MAGI1 and SCRIB and that might be perturbed in tumours induced by oncoviruses or other factors." (PMID 22069443, 2011). "Another interesting observation in this study is that after IR and cisplatin/olaparib treatments, MCF7 MAGI1 KO cells have active AKT signaling, which is known to contribute to tumor progression and drug resistance." (PMID 37566008, 2023). "In conclusion, TMEM220-AS1 acts as a tumor suppressor that inhibits HCC cell proliferation and metastasis, while promoting apoptosis through the miR-484/MAGI1 axis." (PMID 34422806, 2021). "Supporting the tumor suppressive effects of TXNIP and MAGI1, we found that knockdown of TXNIP or MAGI1 in ASXL1+/− K562 cells led to increased proliferation and higher cell viability under serum deprivation." (PMID 32683582, 2021). "A similar positive correlation between MAGI1, ESR1, and GATA3 expression is also found in tumor samples derived from the MMTV-PyMT spontaneous model of BC." (PMID 31963297, 2020). "Conversely, overexpression of MAGI1 suppressed cell migration and invasion in vitro in different CRC cell lines and attenuated primary tumor growth and spontaneous lung metastasis in vivo in an orthotopic model of CRC by inhibiting the Wnt/β-catenin signaling pathway." (PMID 34198584, 2021). "Interestingly, MAGI1 and MAGI2 genetic loci generate a series of long non-coding RNAs that act as a tumor promoter or suppressor in a tissue-dependent manner, by selectively sponging some miRNAs or by regulating epigenetic processes." (PMID 34503076, 2021). "Given the non-metastatic phenotype of these cells it is not surprising that downregulation of MAGI1 alone was not sufficient to allow cancer cells to accomplish the complete metastatic cascade from the primary tumor." (PMID 31963297, 2020). "In contrast, MAGI1 expression levels do not impact TNBC patient prognosis, a patient subgroup characterized by high-grade tumors, and experimental upregulation of MAGI1 in TNBC-like 4T1 tumor cells does not reduce their metastasis capacity." (PMID 31963297, 2020). "Overexpression of MAGI1 in the 4T1 cell line did not affect tumor growth, nor it reduced spontaneous lung metastasis formation." (PMID 31963297, 2020). "Importantly, the increased tumorigenicity of MAGI1 deficient cells is rescued in the absence of AMOTL2 or after inhibition of p38, demonstrating that MAGI1 acts as a tumor-suppressor in luminal BCa by inhibiting an AMOTL2/p38 stress pathway." (PMID 33707576, 2021). "Downregulation of MAGI1 in 67NR cells slightly but significantly increased tumor growth, however we could not detect neither micro- nor macro-metastasis in the lungs." (PMID 31963297, 2020).